IL10 (interleukin 10)
Diseases named in the same sentence as IL10 in open-access papers (continued):
Sharing a sentence is not in itself a finding about the gene and the disease.
malaria (continued). "It has previously been shown that IL-10−/− mice succumb to normally avirulent P. chabaudi chabaudi infections despite comparable - or more effective - control of malaria parasitaemia compared to WT mice." (PMID 18401464, 2008). "Severe malaria has also been associated with increased production of IFN-γ and IL-1β and decreased production of anti-inflammatory cytokines, notably IL-10 and TGF-β." (PMID 18489763, 2008). "In this study we have found that the major source of IL-10 during malaria (Plasmodium yoelii) infection is adaptive regulatory CD4+ T cells." (PMID 18401464, 2008). "Another factor thought to influence clinical outcome of malaria is the fine balance between the pro- and anti-inflammatory cytokines, such as TNFα, IFNγ and IL-10 produced during the infection, that modulate parasite–induced immune responses." (PMID 17460756, 2007). "Anti-inflammatory cytokines, such as IL-10, contribute also to the regulation of the inflammatory response during malaria." (PMID 17460756, 2007). "Plasma IL-10 concentrations were significantly lower in the UI group than in the UM (p = 0.002) and severe malaria groups (p<0.0001), but were similar in the UM, SNCM and CM groups (data not shown)." (PMID 17460756, 2007). "Therefore, this study aims to compare plasma levels of IFN-γ and IL-10 among Sudanese children with severe malaria (SM), uncomplicated malaria (UM) and healthy controls (HC) and to evaluate their diagnostic accuracy using in differentiating SM from UM cases." (PMID 42194890, 2026). "Such IL-10–dominated profiles may reflect immune tolerance or epigenetic reprogramming of monocytes, as seen in asymptomatic malaria cases in Malian adults and children, potentially increasing susceptibility to secondary infections." (PMID 41279035, 2025). "Additionally, we found that secretion of IL-10 by human malaria-naive NK cells is induced in vitro by cytokines IL-15, IL-21, and IL-12." (PMID 40337867, 2025). "We found that many more NK cells from individuals with malaria infection experience could secrete IL-10 as compared with NK cells from malaria-naive individuals." (PMID 40337867, 2025). "We sought to determine whether NK cells from individuals who have undergone many seasonal exposures to Plasmodium infections have a higher propensity to secrete IL-10 than those from malaria-naive individuals." (PMID 40337867, 2025). "Therefore, we chose to assess CD56+ NK cells for expression of IL-10 secretion from malaria-naive and malaria-experienced individuals." (PMID 40337867, 2025). "We hypothesize that increased IL-10 production is due to “peripheral training” of NK cells after repeated exposure to the inflammatory cytokine milieu of malaria; however, genetic elements may also contribute to an increased propensity to make IL-10." (PMID 40337867, 2025). "Also, we report upregulated expression of IL-10 in children with acute malaria, a finding that is in line with what has been previously reported on the polarization of immune responses by IL-10 in children with acute/repeated exposure to malaria and eBL cases." (PMID 41285032, 2025). "An increased production in IL-10 levels has been associated with GCC alleles unlike the mutants ATA for − 1082/-819/-592 IL-10 haplotypes in severe malaria patients." (PMID 40903786, 2025). "Alternatively, other studies also reported that the GCC haplotype was associated with increased IL-10 production unlike the ATA haplotype in patients with severe malaria." (PMID 40903786, 2025). "This could also explain why the IL-1β level in this present study was highest in typho-malaria group with a lower IL-10 level." (PMID 40014608, 2025). "Following cytokine stimulation with IL-15 and IL-21, IL-10 release from NK cells was substantially greater from malaria-experienced individuals in both ADCC (~10-fold increase) and natural cytotoxicity assays (~5-fold increase) that occurred in the presence of IL-12." (PMID 40337867, 2025).
malaria (continued). "Human NK cells can also secrete IL-10, but it is unknown what NK cell subsets produce IL-10 or if this is affected by malaria experience." (PMID 40337867, 2025). "In other studies of experimental malaria, IL-27 appears to be an important cytokine for the development of protective immunity and may be essential for the development of IL-10-producing regulatory CD4 T-cells." (PMID 40972121, 2025). "Contrary to the notion that chronic malaria is immunologically silent, our results suggest that infected chimpanzees undergo significant shifts in cytokine profiles, particularly elevated systemic and cellular IL-10 levels." (PMID 41279035, 2025). "While differences in allele frequencies across populations may partially explain the relationship between IL-10 and malaria, further validation through alternative mechanisms in diverse populations is still required." (PMID 40993672, 2025). "Together, these results suggest that high circulating levels of IL-10 produced by CD4+ T cells contribute to subclinical patent parasitemia by suppressing an otherwise robust inflammatory response in a mouse model of subclinical malaria." (PMID 40972121, 2025). "Another cytokine that proved to be relevant for maternal outcomes was IL-10, which also showed a positive correlation with previous exposure to malaria (r = 0.29) and parasitemia (r = 0.47) (both P < 0.001) and a negative correlation with the gain of maternal weight (r = -0.18; P = 0.010)." (PMID 39495782, 2024). "Therefore, to control the exaggerated pro-inflammatory response, Th1 profile effector cells self-regulate by increasing IL-10 production in malaria (Freitas do Rosario and Langhorne, 2012)." (PMID 39703398, 2024). "However, the IL-10 SNP rs1800896 (-1082 A/G), GCT haplotype, and the rs1800871 (-819T/C), and rs1800872 (-338 592A/C) were associated with a reduced risk of malaria symptoms." (PMID 38404582, 2024). "While IL-10 is an anti-inflammatory cytokine, in severe malaria, its regulatory function may be impaired or overwhelmed by the excessive pro-inflammatory response." (PMID 38694310, 2024). "However, the complexity of the role of IL-10 in malaria pathogenicity during pregnancy requires further study, as the relationship between this cytokine and newborn weight and height is still uncertain." (PMID 39495782, 2024). "Patients with malaria present reduced levels of IL-10, an anti-inflammatory interleukin, which may be related to thermal hyperalgesia occurring in mice infected with P. berghei, especially in the late stages of infection." (PMID 39703398, 2024). "IL-10, a key cytokine, has an essential regulatory function in controlling the inflammatory response and preventing or ameliorating a wide range of clinical manifestations during malaria." (PMID 38265549, 2024). "Additionally, the levels of the peripheral cytokines IL-6 and IL-10 were elevated in infected women, which were correlated with previous maternal exposure to malaria, increased parasitemia, and reduced maternal weight gain and the gestational age at delivery." (PMID 39495782, 2024). "Similarly, children with malaria had relatively raised plasma levels of IL‐10, which is comparable with other studies." (PMID 39240033, 2024). "This suggests the possibility of using IL-10 as a severity marker for malaria." (PMID 36668942, 2023). "The roles of pro-inflammatory and anti-inflammatory cytokines in the pathogenesis of severe malaria have been widely studied, but the role of IL-10 in the pathogenesis of severe malaria remains unclear." (PMID 36668942, 2023). "In malaria, tissue is protected from injury by IL-10 production." (PMID 37492527, 2023). "Moreover, only IL-10 and IL-6 levels were significantly higher in children with severe malarial anemia compared to children with uncomplicated malaria who had significantly lower IL-10 levels than children with moderate malarial anemia." (PMID 36787308, 2023).
malaria (continued). "Similarly, as has been shown previously, there were higher than normal levels of the predominantly anti-inflammatory cytokine IL-10 in the CM group compared to levels observed in healthy controls and in the other clinical malaria controls." (PMID 37060041, 2023). "In addition, by enhancing the proliferation of B cells, IL-10 contributes towards the humoral response to malaria." (PMID 37060041, 2023). "Despite being considered a highly inflammatory disease, P. vivax infection triggers substantial IL-10 production and although the immune response mediated by IL-10 during malaria is well established, the main sources, and what triggers its production are not fully understood." (PMID 37545509, 2023). "Levels of IL-10 were significantly higher in severe and moderate malarial anemia compared to the uncomplicated malaria group [395.80 (186.10–563.40) pg/ml vs. 26.58 (9.79–260.70) pg/ml; p = 0.014 and 293.38 (115.30–579.69) pg/ml vs. 26.58 (9.79–260.70) pg/ml; p = 0.031, respectively]." (PMID 36787308, 2023). "To further characterise malaria-specific nnCD4+ T cell subsets at a molecular level, we performed RNA sequencing on IL-10+IFNγ+TNFα− and IL-10−IFNγ-TNFα+ nnCD4+ T cells isolated from three DPSP primigravid pregnant women at enrolment using a cytokine capture assay (>200 cells per sample)." (PMID 37634385, 2023). "T cell senescence together with alterations in the IL-10 might lead to a major immune dysfunction and, subsequently, the development of severe malaria." (PMID 36668942, 2023). "Furthermore, the cytokines TNF and IL-10 have also been shown to distinguish between severe malaria anaemia (SMA) and high parasitaemia in African children." (PMID 37060041, 2023). "CD4+ T cell STING is required for optimal IFN-γ and IL-10 production in experimental malaria." (PMID 37781920, 2023). "Moreover, increases in the IL-6/IL-10 ratio have been reported to be a predictor of death in patients with malaria." (PMID 36668942, 2023). "The roles of anti-inflammatory cytokines in the pathogenesis of severe malaria have been widely studied, and the role of IL-10 in the pathogenesis of severe malaria remains unclear." (PMID 36668942, 2023). "IL10 has shown to protect the host in various parasitic diseases, such as malaria, where this cytokine counteracts the proinflammatory response induced by P. falciparum, and where deficiency of this host protection mechanism may occur in severe forms." (PMID 37440604, 2023). "In addition, a recent study in experimental model have showed that the regulatory cytokine IL-10 plays an essential role in promoting germinal center B cell responses during malaria in early stage of infection." (PMID 36787308, 2023). "In addition, most studies have provided less information from a relatively small number of participants, which precludes the collection of comprehensive data on IL-10 in the pathogenesis of the severity of malaria." (PMID 36668942, 2023). "Furthermore, we previously showed that type I IFNs act on dendritic cells to suppress the development of Th1 cells while promoting Il10 gene transcription in a model of experimental malaria." (PMID 37781920, 2023). "Co-infected mice exhibited decreased levels of pro-inflammatory cytokines (i.e. IFN-γ, TNF-α, and IL-12p70), in contrast to the level of anti-inflammatory cytokine IL-10, which was boosted in mouse serum, suggesting a protective function of IL-10 against complicated malaria." (PMID 37492527, 2023). "Moreover, increased IL-10 levels were reported to be an important indicator of severe malaria in older adults, particularly in patients with P. knowlesi malaria." (PMID 36668942, 2023). "In view of our results, IL-10 might be a good marker of malaria pathogenesis as well as serves as an indicator of severe anemia during a malaria infection." (PMID 36787308, 2023).
malaria (continued). "Together, these data suggest that both the overall magnitude, and relative proportion, of malaria-specific nnCD4+ T cell responses differ across gravidity, with primigravid women tending to have a more IL-10 producing response, and multigravid women tending to have a more TNFα producing response." (PMID 37634385, 2023). "Hence, these results indicate that CD4+ T cell STING promotes IL-10 production while suppressing IFN-γ production in a cell-intrinsic manner in vivo in experimental malaria." (PMID 37781920, 2023). "First, some full texts of the relevant studies that reported IL-10 in patients with severe malaria may have been missed due to the limitation of access to some specific databases." (PMID 36668942, 2023). "IL-10 has been reported to be involved in severe malaria, particularly severe anemia." (PMID 36668942, 2023). "By analysing malaria-driven transcriptional changes at the subset level, we not only increase our understanding of how malaria modulates specific immune cell subsets, but also identify IL-10+ Bregs as a major tolerogenic response in human adaptive immune cells during infection." (PMID 37968278, 2023). "Induction of IL-10 production is frequently observed in Pv-infected patients and previous studies have suggested a role for this cytokine in controlling immunopathology in human malaria." (PMID 37545509, 2023). "Only 3 epitopes belonging to murine malaria parasite P. berghei are positive for IL-10 induction." (PMID 35277125, 2022). "Here, we observed that IL-10 and IL-6 levels were 1.3- to 18.0-fold lower in those with malaria-intestinal parasite co-infections (both helminths and protozoa) than in those with plasmodial mono-infections, although they were still higher than those in uninfected participants." (PMID 35421083, 2022). "However, we found a higher level of IL-10 during active malaria at both visits and for symptomatic and asymptomatic infections." (PMID 35911674, 2022). "Interestingly, the promoter region for IL-10 was also significantly more accessible in convalescent child patients with malaria than adults at the corresponding treatment stage." (PMID 35642634, 2022). "Similarly, lethality of malaria is thought to be due to the overproduction of IL-10 in the early stage of infection." (PMID 35719355, 2022). "Additionally, IFN-γ/IL-10 co-producing cells also have been described as a dominant population of CD4+ T cells in acute malaria infection with malaria parasites." (PMID 35277125, 2022). "STHs would be protective against malaria according to the IL-10/TNF-α ratio, while according to the IL-10/IL-6 ratio, intestinal protozoa may have a detrimental effect." (PMID 35421083, 2022). "However, in Malaria patients and co-infected there was a positive correlation between the IL-6 and IL-10 levels (P < 0.0001)." (PMID 35749690, 2022). "Whether the Tr1-like cells are bona fide Tr1 cells instead of Th1 cells expressing IL-10 remains to be seen, but regardless, the IL-10-producing CD4+ T cells in malaria limit disease-associated pathology and may contribute to clinical immunity." (PMID 36389662, 2022). "Additionally, the production of IL-12 by monocytes is repressed by IL-10, which is necessary for induction of a protective immune response against malaria and shifting to a pro-inflammatory cytokine response." (PMID 35719355, 2022). "Moreover, IL-10-producing Foxp3+Tbet+CD4+ regulatory T cells are considered an important source of IL-10 during malaria pathogenesis." (PMID 35277125, 2022). "Additionally, IL-10 is the primary anti-inflammatory cytokine in malaria, and the symptomatology becomes less severe as its concentration increases." (PMID 36237427, 2022). "IL-10 concentration has been interrelated with parasite density implying that IL-10 has an important immunoregulatory role, pronounced in both experimental and human models of malaria." (PMID 35277125, 2022).
malaria (continued). "The present investigation shows a rapid increase of IL-10 by lethal malaria parasite was observed and that may be indicative of immune suppression leading to increased parasitaemia and host mortality." (PMID 35109868, 2022). "In addition, multiple pieces of evidence for the increased IL-10 level in the serum of malaria patients are available." (PMID 35625397, 2022). "Additionally, the immunosuppressive activity of testosterone in our malaria model is mediated, at least in part, by IL-10; this cytokine negatively regulates the proinflammatory response." (PMID 36237427, 2022). "Additionally, to prevent severe malaria, IL-4 and IL-10 can directly downregulate IL-6, TNF-α, and IL-1β." (PMID 35820892, 2022). "Whether mDCs from malaria-naïve US individuals are also capable of responding to the parasite with IL-10 secretion will have to be addressed in future experiments." (PMID 33407502, 2021). "In the current study, we sought to identify if a critical temporal window exists for IL-10, the cell subset(s) responsible for provision of IL-10 to B cells, and the mechanism by which IL-10 functions to promote B cell responses and humoral immunity during experimental malaria." (PMID 33529242, 2021). "The genes involved in host immune response and binding of the malaria parasite, particularly TGFβ1, IL10 and ICAM1 may play a more significant role in malaria parasitemia in P. falciparum than in P. vivax infection." (PMID 34698295, 2021). "In addition, a Sudanese study reported high level of IL-10 was reported among malaria parasitemic children." (PMID 35223394, 2021). "Indeed, Il-10 has been extensively described in murine malaria models and human studies as an important regulatory factor." (PMID 33407502, 2021). "Similarly, significant elevated level of proinflammatory IL-6 and IL-10 was reported in Malian children with severe-malaria." (PMID 35223394, 2021). "The cytokine/parasite density ratios also pointed in this direction as the IL-10/parasite density ratio was highest in asymptomatic malaria cases while the pro-inflammatory IL-6/parasite density ratio was highest in patients with clinical malaria." (PMID 34177883, 2021). "Serum IL-10 and IL-6 significantly elevated with increased malaria density (p<0.0001)." (PMID 35223394, 2021). "Given that Tr1-derived IFNγ and IL-10 cytokines negatively regulated Tfh cell responses in mice models of malaria, overcoming or blocking parasite-specific Tr1 cells in malaria-exposed children may be required to optimize vaccine responsiveness." (PMID 36845571, 2021). "IL-10 has a fundamental role in response to Plasmodium infections, directly affecting dampening the inflammation-driven cytokine storm, modulating the immune response, and limiting the tissue damage, reducing odds of severe malaria." (PMID 34727121, 2021). "The most studied ones in malaria are Br1, which include all B cells producing IL10." (PMID 34684226, 2021). "Future studies are needed to assess a panel of IL-10-producing cell types that may contribute to the immuno-regulatory environment in children infected with malaria and diagnosed with eBL." (PMID 34771539, 2021). "Clinical malaria models and human studies have shown that IL-10 could inhibit antiparasitic immunity." (PMID 34540719, 2021). "In the end, we wanted to confirm whether IL-10 maintain the delicate balance between pro- and anti-inflammatory immune responses of host and malaria parasite and modulates the host’s immune system to produce local/circulatory regulatory T cells (Tregs)." (PMID 33562617, 2021). "On the other hand, although the majority of markers with significant perturbances were noted in symptomatic patients, the comparison of malaria groups also identified augmented expression of MDP levels of IL-10 and indirect bilirubin in asymptomatic individuals." (PMID 34727121, 2021).